MBL2 (mannose binding lectin 2)
Diseases named in the same sentence as MBL2 in open-access papers (continued):
Sharing a sentence is not in itself a finding about the gene and the disease.
HIV-1 infection (3 papers, 2015 to 2021). The type species of lentivirus and the etiologic agent of acquired immunodeficiency syndrome (AIDS). "A statistical relationship was observed between MBL2 gene polymorphisms and HIV-1 infection in the South Brazilian, Italian, and Chinese Han populations." (PMID 34154540, 2021). "Many genetic epidemiological studies have explored the relationship between MBL2 gene mutation and HIV-1 infection, but the results are controversial and inconclusive." (PMID 34154540, 2021). "Analysis was done to determine if MBL2 genetic and promoter region variants were associated with HIV-1 infection." (PMID 25830474, 2015). "The available evidence on the association of polymorphism in the MBL2 promoter region with HIV-1 infection is still conflicting." (PMID 25830474, 2015). "Distribution of participants between MBL2 genotypes and promoter region haplotypes, participants stratified according to HIV-1 infection status." (PMID 25830474, 2015). "We found plasma MBL deficiency and MBL2 gene and promoter region variants to play no role in HIV-1 infection, but high plasma MBL levels and the heterozygous promoter genotype LY and homozygous LL increased susceptibility to schistosoma infections." (PMID 25830474, 2015). "None of these MBL2 genotypes and promoter variants were associated with HIV-1 infection." (PMID 25830474, 2015).
leishmaniasis (3 papers, 2012 to 2022). Infectious disease that is transmitted through the bite of hematophagous female phlebotomine sand flies. "This systematic review included case-control studies of the genetic association of variants (rs11003125, rs7096206, rs7095891, rs5030737, rs1800450, and rs1800451) in the MBL2 gene and the risk of developing leishmaniasis." (PMID 35331599, 2022). "To evaluate, through a systematic review, case-control studies of the genetic association of variants in the MBL2 gene and the risk of developing leishmaniasis." (PMID 35331599, 2022). "High level of MBL and associated genetic variants of MBL2 haplotypes are therefore found more frequently in leishmaniasis patients than in healthy controls." (PMID 22457818, 2012). "Some studies have been conducted previously to assess the effects of the MBL2 gene polymorphisms on the evolution of the infection in leishmaniasis, with contradictory results due to the small sample size, which lacks adequate power to detect the effects of MBL2 gene polymorphisms on leishmaniasis." (PMID 35331599, 2022). "To date, no systematic review has been performed on MBL2 gene variants and leishmaniasis." (PMID 35331599, 2022).
liver cancer (3 papers, 2015 to 2023). An epithelial or non-epithelial malignant neoplasm that arises from the liver. "MBL2 expression was significantly lower in liver cancer than in normal tissue and was hardly expressed in other tumors." (PMID 37835594, 2023). "After a further analysis of immune-regulation-related genes, we successfully identified seven CTC-related immune regulation genes, and MBL2 was found to be significantly downregulated in high-CTC liver cancer tissues." (PMID 37835594, 2023). "CCK-8 and plate cloning experiments were performed to verify the regulatory effect of MBL2 on the proliferation of liver cancer cells." (PMID 37835594, 2023). "To verify the effect of MBL2 on the invasive ability of liver cancer cells, we used Transwell® and wound healing assays." (PMID 37835594, 2023). "Subsequently, we evaluated the expression level of MBL2 in liver cancer and adjacent normal tissues of liver cancer patients using immunohistochemistry." (PMID 37835594, 2023). "Using TCGA’s liver cancer tissue miRNA database, we discovered a significant correlation between MBL2 and miR-34c-3p." (PMID 37835594, 2023). "Nucleotide substitution rates were also higher within the medium/low MBL2 production group in all positions described to have an influence in liver cancer development, except for A1499G." (PMID 27824315, 2016). "It was also revealed through literature that MBL2 has strong secretory nature and strong presence in liver cancer tissue and cell line (HepG2)." (PMID 26414287, 2015). "To test this hypothesis, we simultaneously analyzed datasets from public platforms and found that MBL2 was downregulated in liver cancer specifically." (PMID 37835594, 2023). "The expression of MBL2 was markedly lower in liver cancer tissues compared to non-cancerous tissues." (PMID 37835594, 2023).
parasitic infections (3 papers, 2015 to 2017). "Very little is known about the association of MBL2 with parasitic infections." (PMID 28824344, 2017). "Polymorphism in the MBL2 gene lead to MBL deficiency, which has been shown to increase susceptibility to various bacterial, viral and parasitic infections." (PMID 25830474, 2015).
pneumococcal meningitis (3 papers, 2013 to 2017). An acute purulent infection of the meninges and subarachnoid space caused by Streptococcus pneumoniae, most prevalent in children and adults over the age of 60. "Our study provides the first data on MBL deficiency in pneumococcal meningitis, and shows MBL deficiency caused by genetic variants in MBL2 exon 1 to be associated with a substantial increase in susceptibility to pneumococcal meningitis." (PMID 23741476, 2013). "We assessed the influence of genetic variation in MBL2 on susceptibility, outcome and causative serotype of pneumococcal meningitis in a prospective nationwide cohort study including 299 white patients and 216 controls." (PMID 23741476, 2013). "Patients homozygous for variant alleles in exon 1 of MBL2 had 8-fold increased susceptibility to pneumococcal meningitis." (PMID 23741476, 2013). "The risk of contracting pneumococcal meningitis was substantially increased for white individuals homozygous with the defective MBL2 0/0 genotype (odds ratio [OR] 8.21, 95% confidence interval [CI] 1.05–64.1; p = 0.017)." (PMID 23741476, 2013). "Distribution of MBL2 polymorphisms in white patients with pneumococcal meningitis and controls." (PMID 23741476, 2013). "An interesting observation was that all pneumococcal meningitis patients with the MBL2 0/0 genotype survived, as compared to 9% mortality among patients with the A/A and A/0 genotype." (PMID 23741476, 2013).
respiratory infections (3 papers, 2012 to 2020). "An earlier report on the role of MBL2 polymorphisms and recurrent respiratory infections in children suggested that it was the coexistence of (partial) immune defects, rather than any one single immunological aetiologic factor that was associated to the disease outcome." (PMID 22363494, 2012).
schistosomiasis (3 papers, 2014 to 2020). An infectious disease caused by parasitic trematodes of the genus Schistosoma that colonize human blood vessels and release eggs that can cause granulomatous reactions leading to acute (swimmer's itch or acute schistosomiasis syndrome) or chronic disease. "The MBL2 polymorphisms and MBL serum levels were involved in different infectious diseases such as malaria and schistosomiasis and in autoimmune diseases such as systemic lupus erythematosus and ankylosing spondylitis." (PMID 24751721, 2014).
Thrombocytopenia (3 papers, 2009 to 2025). A reduction in the number of circulating thrombocytes. "Previously, we have demonstrated that MBL2 gene polymorphism is correlated with the risk of thrombocytopenia elicited by dengue virus and in this study we saw a significant correlation between the MBL protein and DHF." (PMID 19707565, 2009). "Alleles of MBL2 gene that are associated with higher concentrations of functional MBL, have been shown to be associated with thrombocytopenia in dengue infected patients." (PMID 22559908, 2012).
urinary tract infection (3 papers, 2013 to 2019). "We found a higher frequency of urinary tract infection and herpes stomatitis in infants without measurable MBL2 levels at 24 months-follow-up." (PMID 28558032, 2017).
adenoid hypertrophy (2 papers, 2022 to 2025). "Furthermore, prior works showed that the MBL2 (SNP 49 C/T rs5030737) gene polymorphism; the AG + GG and AG genotypes at TLR4-D299G; Ugrp2; and the 2R, 2R, Il-1Ra and T, and T IL-1b genotypes were associated with an increased risk of developing adenoid hypertrophy." (PMID 35207552, 2022).
allergic asthma (2 papers, 2021 to 2025). A asthma with a basis in a pathological type I hypersensitivity reaction. "Moreover, single nucleotide polymorphisms in the genes encoding the fungal recognition receptors dectin-1 (CLEC7A) and mannose-binding lectin (MBL2) have been associated with allergic asthma susceptibility." (PMID 34060330, 2021).
Behçet's disease (2 papers, 2017 to 2021). "MBL2 polymorphism has been linked with Behçet’s disease, cellulitis, and ulcerations." (PMID 33790889, 2021).
chronic kidney disease (2 papers, 2018 to 2025). Impairment of the renal function secondary to chronic kidney damage persisting for three or more months. "For the other replicated cis-pQTLs, we found that they were significantly associated with highlight scatter reticulocyte count (C8A and C8B), chronic kidney disease and reticulocyte count (MBL2)." (PMID 39989961, 2025).
filariasis (2 papers, 2015 to 2021). "The studied population is also endemic to filariasis, and a previous study by our group (unpublished results), and others had shown an association between MBL2 variants with susceptibility to lymphatic filariasis." (PMID 26284055, 2015).
Insulin resistance (2 papers, 2014 to 2020). Increased resistance towards insulin, that is, diminished effectiveness of insulin in reducing blood glucose levels. "Recently, MBL2 has been found to play a role in the development of insulin resistance and gestational DM, and functional variations in MBL2 can increase DM susceptibility." (PMID 33603663, 2020). "Estimation of insulin resistance and validated MBL measurements and determination of genetic MBL2 variants and statistical analysis completed the study." (PMID 25281004, 2014).
juvenile idiopathic arthritis (2 papers, 2006 to 2008). Juvenile idiopathic arthritis (JIA) is the term used to describe a group of inflammatory articular disorders of unknown cause that begin before the age of 16 and last over 6 weeks. "The aim of our study was to determine whether genetically determined MBL deficiency is associated with susceptibility to juvenile rheumatoid arthritis (JRA) and whether MBL2 genotypes are associated with JRA severity." (PMID 18334024, 2008).
kidney failure (2 papers, 2021). An acute or chronic condition that is characterized by the inability of the kidneys to adequately filter the blood. "After adjustment for clinical and pathologic risk factors in multivariate analysis, only one variant in MBL2 (rs1800450) was associated with progression to kidney failure in IgAN patients." (PMID 34682837, 2021). "Sequencing of the genes for MBL and L-ficolin, MBL2 and FCN2, identified association between future kidney failure and the MBL2 variant rs1800450-A in IgAN." (PMID 34379175, 2021).
mastitis (2 papers, 2018 to 2021). Inflammation of breast tissue during lactation or postpartum due to an obstructed duct or infection. "Polymorphisms in the collagenous lectin genes have been shown in previous studies to contribute to infectious disease susceptibility, and in cattle, mutations in two collagenous lectin genes (MBL1 and MBL2) are associated with mastitis." (PMID 29744529, 2018). "On the other hand, the direct association between mastitis and MBL1, MBL2, NOD2 and M-SAA3.2 genes has not been fully explored so far." (PMID 33535694, 2021).
multiple sclerosis (2 papers, 2023 to 2026). A progressive autoimmune disorder affecting the central nervous system resulting in demyelination. "These comprise variants within genes associated with various types of human cancer (MAD1L1), Joubert syndrome 23 (KIAA0586), hair disorders (PADI3), mannose-binding lectin deficiency (MBL2), and multiple sclerosis (IL4R)." (PMID 36404349, 2023).
nephritis (2 papers, 2012 to 2017). Inflammation of renal tissue. "Variants of the MBL2 gene associated with lower plasma MBL levels have been associated with susceptibility to SLE and the development of nephritis." (PMID 23068019, 2012).
Nephropathy (2 papers, 2016 to 2019). A nonspecific term referring to disease or damage of the kidneys. "Finally, whether the contribution of genetic deficiencies in MBL2 to renal disease progression is specific to IgAN and the underling mechanism require further study." (PMID 30967869, 2019).
Obesity (2 papers, 2015 to 2020). Accumulation of substantial excess body fat. "A keyword search for "MBL2," "deficiency," and "obesity" pointed to clinical findings that an MBL2 deficiency can increase the risk of obesity." (PMID 26694100, 2015).
peritonitis (2 papers, 2015 to 2019). Inflammation of the peritoneum (tissue that lines the abdominal wall and covers most of the organs in the abdomen). "Our large sample collection enabled us to also examine MBL2 genotype associations with survival in a number of predefined homogeneous subgroups, including younger age groups, UK patients only, patients with CAP, those with pneumococcal pneumonia, and patients with peritonitis." (PMID 25969530, 2015).
pneumococcal pneumonia (2 papers, 2013 to 2015). A febrile disease caused by STREPTOCOCCUS PNEUMONIAE. "Three studies were performed in pneumococcal pneumonia patients, and were only included if the MBL2 genotype frequencies of bacteremic patients was specified." (PMID 23741476, 2013).
preeclampsia (2 papers, 2015 to 2024). Preeclampsia is a hypertensive disorder of pregnancy that is characterized by new-onset hypertension with proteinuria presenting after 20 weeks of gestation, and depending on mild or severe forms may initially present with severe headache, visual disturbances, and hyperreflexia. "Furthermore, the investigation identified a number of genetic variants in the genes of ADAMTS13, C3, CFH, CFB, thrombomodulin, MBL2, and MASP2 that were significantly linked with the occurrence of preeclampsia, according to the results of analyses A and B." (PMID 38673014, 2024).
rheumatic fever (2 papers, 2016 to 2018). A post-bacterial multisystem inflammatory disease occurring as a post-infectious, nonsuppurative sequela of untreated streptococcus pyogenes (Group A streptococcus [GAS]) pharyngitis, and mainly occurs in individuals aged 5 to 15 years. "In addition, MBL2 genotypes associated with high MBL levels were shown to increase the risk of acute and chronic carditis in patients with rheumatic fever, whereas O alleles were protective." (PMID 26745156, 2016).
spinal tuberculosis (2 papers, 2018 to 2024). "In the present study, we identified the roles of MBL2, CD14 and TNF-α gene polymorphisms in the susceptibility to spinal tuberculosis in a Chinese population." (PMID 29298876, 2018).
staphylococcus aureus infection (2 papers, 2019 to 2020). An infectious process in which the bacteria Staphylococcus aureus is present. "In the early stage of infection, MASP1, MBL2, CFB, loc396877, loc100627396 linked complement and coagulation cascades with Staphylococcus aureus infection pathway, and C7, loc100736136 linked the Staphylococcus aureus infection with the prion disease pathway." (PMID 32632500, 2020).
systemic sclerosis (2 papers, 2014 to 2020). A chronic disorder, possibly autoimmune, marked by excessive production of collagen which results in hardening and thickening of body tissues. "On the other hand, two studies found an association between high ficolin-2 and MBL plasma levels and systemic sclerosis associated ILD (SSc-ILD), which was supported by a higher frequency of wild-type FCN2 and MBL2 genotypes in SSc-ILD patients." (PMID 33101280, 2020).
acute respiratory distress syndrome (1 paper, 2013). Progressive and life-threatening pulmonary distress in the absence of an underlying pulmonary condition, usually following major trauma or surgery. "Increased susceptibility and worse outcome in 212 Caucasian patients with acute respiratory distress syndrome (ARDS) were also observed in presence of MBL2 gene polymorphisms." (PMID 24223476, 2013).
adenoma (1 paper, 2014). A neoplasm arising from the epithelium. "Recently, expression of the MBL2 gene in papillary thyroid carcinoma tissue specimens was shown to be higher than in those from adenoma or normal thyroid glands." (PMID 25038892, 2014).
Alzheimer disease (1 paper, 2018). A progressive, neurodegenerative disease characterized by loss of function and death of nerve cells in several areas of the brain leading to loss of cognitive function such as memory and language. "Interestingly, among the deregulated proteins associated to Alzheimer’s disease, we found previously reported AD-associated proteins, including the accumulation of GATA4 and Chromogranin-A, or MBL2, whose over-expression has been described in the surrounding of blood vessels in AD brain patients." (PMID 29541381, 2018).
atopic eczema (1 paper, 2013). A common chronic pruritic inflammatory skin disease with a strong genetic component. "MBL- deficient women (according to both serum MBL levels after delivery and according to the MBL2 genotypes) had virtually no history of atopic eczema and asthma." (PMID 24339961, 2013).
atypical hemolytic-uremic syndrome (1 paper, 2021). A rare, genetic thrombotic microangiopathy due to dysregulation of the alternative complement pathway and characterized by the triad of hemolytic anemia, thrombocytopenia, and acute renal dysfunction. "The 3F8 anti-MBL-2 monoclonal antibody was administered to a murine model of atypical hemolytic uremic syndrome and was shown to attenuate C3d deposition and renal injury, suggesting that MBL2 inhibition is a mitigating factor in vivo." (PMID 33790889, 2021).
bipolar disorder (1 paper, 2023). A disorder of the brain that causes unusual shifts in mood, energy, activity levels and the ability to carry out day-to-day tasks. "In addition, MBL2 (encodes mannose-binding lectin 2), which is implicated in mannose metabolism, has been found to be associated with bipolar disorder in genetic studies, supporting the causal role of this metabolite in bipolar disorder." (PMID 37333177, 2023).
brain injuries (1 paper, 2020). "The possible role of MBL2 gene variants in influencing the severity of post-asphyxia brain injuries is still unexplored." (PMID 33042903, 2020).
C. perfringens infection (1 paper, 2025). "Moreover, the findings underscore a coordinated effort of the host to mitigate the C. perfringens infection via activating immune (a.o., C3, CFH, MASP2, MBL2) and acute phase (CP, ORM, TF, ExFAB) related proteins." (PMID 40275387, 2025).
carotid atherosclerosis (1 paper, 2012). A thickening and loss of elasticity of the walls of carotid arteries that occur with formation of atherosclerotic plaques. "The role of mannose-binding lectin (MBL2) genotype in restenosis after eversion endarterectomy in patients with severe carotid atherosclerosis has been also studied." (PMID 22489270, 2012).
Chagas disease (1 paper, 2016). A parasitic infection caused by Trypanosoma cruzi. "Beside these differences in population structure, functional differences among the MBL2*B, C and D variants regarding MASP-2 coupling and serum concentration of low-mass oligomers may explain opposite association outcomes and should be further investigated in the context of Chagas disease." (PMID 26745156, 2016).
Chlamydia infection (1 paper, 2016). "However, certain polymorphisms in the MBL2 gene have beenassociated with increased risk of Chlamydia infection." (PMID 27982280, 2016).